SNORA80A (small nucleolar RNA, H/ACA box 80A)
Synonyms: ACA67; SNORA80
Gene: Small nucleolar RNA gene on chromosome 21 (32,377,187 to 32,377,322, reverse strand). Ensembl gene ENSG00000200792.
Gene Ontology:
Biological process: RNA processing
Cellular component: nucleolus
Homologues: Orthologues: chimpanzee SNORA80A (99% identical), macaque SNORA80A (97% identical). Paralogues in human: SNORA80B (92% identical), SNORA80C (90% identical), SNORA80D (88% identical), SNORA80E (76% identical).
Diseases named in the same sentence as SNORA80A in open-access papers:
SNORA80A is named in the same sentence as 2 diseases in open-access papers, as found by Europe PMC text mining. Sharing a sentence is not in itself a finding about the gene and the disease.
SNORA80A shares sentences with these, for which no sentence is quoted: cancer (1 paper); lung carcinoma (1).